KDM1A (lysine demethylase 1A)
Diseases named in the same sentence as KDM1A in open-access papers (continued):
Sharing a sentence is not in itself a finding about the gene and the disease.
breast carcinoma (continued). "The removal of histone H3K4me2 demethylase activity of the LSD1/KDM1A histone demethylase in MCM7 human breast cancer cells reduces the expression of the RNA-induced silencing complex, leading to the increased transcription of endogenous retroviral elements and dsRNA synthesis." (PMID 34638614, 2021). "In addition, the mutation of KDM1A in BRCA exhibited poor survival, yet the high DNA methylation of KDM1A foreboded a better survival prognosis of breast cancer via decreasing KDM1A expression." (PMID 34925656, 2021). "In addition, our analytic workflow for KDM1A will contribute to designing future experimental studies and future drug development for patients with breast cancer." (PMID 33799951, 2021). "Previous studies have demonstrated that high KDM1A expression is related to worse prognoses in various types of solid tumors, such as nonsmall cell lung cancer, colorectal cancer, neuroblastoma, prostate cancer and breast cancer." (PMID 33799951, 2021). "However, the specific mechanism of how high KDM1A expression affects breast cancer remains poorly understood." (PMID 33799951, 2021). "Our study revealed higher KDM1A expression in breast cancer tissue than in normal tissue." (PMID 33799951, 2021). "The overexpression of KDM1A can be considered an early event in breast cancer tumorigenesis." (PMID 29921310, 2018). "The fundamental role of KDM1A in prostate and breast cancer will presumably support a rapid realization of clinical phase I/II studies with KDM1A inhibitors in adults, which will in turn open new avenues for treatment of pediatric embryonal tumors, including medulloblastomas." (PMID 24252778, 2013). "We suggest that high expression of KDM1A may play critical oncogenic roles in breast cancer." (PMID 33799951, 2021). "In addition, KDM1A has been regarded as a potential target for anticancer drug development, as a number of reports indicate its high levels in many carcinomas, including prostate cancer, lung cancer, and breast cancer." (PMID 34307695, 2021). "Moreover, the phosphorylation levels of KDM1A were upregulated in breast cancer, UCEC, and LUAD, and the phosphorylation of KDM1A at S131 and S137 was experimentally supposed to play a role in regulating RNF168-dependent 53BP1 recruitment in response to DNA damage and resisting DNA damaging agents." (PMID 34925656, 2021). "The histone demethylase KDM1A, which functions to repress and activate transcription by mediating histone H3K4me1/2 and H3K9me1/2 demethylation, respectively, was reported to be present at significantly lower levels in breast cancer samples compared with normal tissues." (PMID 32241272, 2020). "Conversely, histone demethylases such as LSD1 (KDM1A) and LSD2 are overexpressed in several cancers, including AML, small cell lung cancer (SCLC), breast cancer, and colorectal cancer (CRC)." (PMID 40761481, 2025). "Survival analysis showed that compared to low KDM1A expression, high KDM1A expression is related to poor DFS and DSS in patients with breast cancer." (PMID 33799951, 2021). "In keeping, we showed that ZNF750 negatively regulates cell migration and invasion in breast cancer cells; in particular, ZNF750 binds and recruits KDM1A and HDAC1 on the LAMB3 and CTNNAL1 promoters." (PMID 33298895, 2020). "HOTAIR binds to lysine-specific histone demethylase 1A (KDM1A) and polycomb repressive complex 2 (EZH2) in the 5′ and 3′ regions, repressing the transcription of the homeobox D cluster (HOXD) family genes in the progression of breast cancer and CRC." (PMID 38294554, 2024). "In breast cancer cells, the HDAC inhibitor was applied as a therapeutic approach to attenuate disease progression, which was subjected to regulation of crosstalk between KDM1A and histone deacetylation." (PMID 34350095, 2021). "Nevertheless, the molecular mechanisms of carcinogenesis and clinicopathological differences according to KDM1A expression in breast cancer have not yet been completely explained." (PMID 33799951, 2021).
breast carcinoma (continued). "Likewise, the glycolytic activity of breast cancer cells can be promoted through the repression of the FBP1 and glucose-6-phosphate (G6P) genes by lysine demethylase 1A (LSD1)-dependent demethylation of specific activating histone methylation marks." (PMID 34572926, 2021). "Third, the relationship between expression of KDM1A by intrinsic breast cancer subtypes and prognosis was not analyzed." (PMID 33799951, 2021). "Furthermore, the HOTAIR-mediated KDM1A/PRC2 complex positively regulates the transcription factor NFAT5, which is involved in angiogenesis and the progression of breast cancer." (PMID 29921310, 2018). "In addition to KDM1A, its homolog KDM1B is highly expressed in breast cancer, particularly in invasive tumors." (PMID 29921310, 2018). "Indeed, KDM1A is highly expressed both in hematological malignancies, including acute myeloid leukemia, and solid tumors, such as CRC, prostate, lung, brain, and breast cancers." (PMID 37385999, 2023). "Among them, alisertib, which showed a high negative correlation between high KDM1A expression and LN IC50, was identified as the most sensitive anticancer drug for breast cancer cell lines." (PMID 33799951, 2021).
prostate carcinoma (120 papers, 2011 to 2026). A carcinoma that arises from epithelial cells of the prostate gland. "Although there are studies that describe very little to no overexpression of KDM1A in prostate cancer cell lines, the overexpression of KDM1A has been found to be associated with prostate cancer progression and recurrence." (PMID 29921310, 2018). "Furthermore, in prostate cancer, the increased expression of KDM1A is associated with cancer progression." (PMID 37958805, 2023). "Similarly, prostate cancer has also been thought to be linked to KDM1A due to KDM1A-mediated transcriptional regulation of AR, and KDM1A inhibition decreases prostate cancer proliferation." (PMID 33029224, 2020). "Furthermore, we determined that RNA-mediated interactions between BAZ2A and TOP2A and KDM1A repress genes critical to PCa and may prove to be useful to stratify prostate cancer risk and treatment in patients." (PMID 37184661, 2023). "It has been reported that KDM1A can be involved in prostate cancer by increasing chromatin accessibility of the FOXA1 promoter." (PMID 38295985, 2024). "In our analysis, twelve histone demethylases showed gene upregulation in prostate cancers, of which six (KDM1A, KDM4B, KDM5B, KDM5C, KDM7A, and PHF8) were in line with previous reports." (PMID 36776320, 2023). "Increased expression of KDM1A and KDM5B is implicated in many cancer types, including prostate cancer (PCa)." (PMID 37152294, 2023). "The BAZ2A-TAM domain, in association with RNA, promotes the interaction with TOP2A and KDM1A that serves to repress genes critical to prostate cancer progression." (PMID 37184661, 2023). "In a study about prostate cancer, we found KDM1A was conspicuously increased in relapse prostate cancer tissues, and KDM1A silencing inhibited cell proliferation." (PMID 36941992, 2023). "LSD1/KDM1A Interaction of LSD1 with transcription factors activates expression of a network of genes favouring growth of CRPC prostate cancers." (PMID 35406676, 2022). "After a well‐known ERRα regulator, KDM1A, was recently observed to be involved in the corruption of vitamin D signaling in prostate cancer, we assessed the ERRα‐KDM1A connection in the VDR pathway of BC." (PMID 34003583, 2022). "Consistently, hsa-miR-137 has been proven to target KDM1A mRNA in the progression of prostate cancer." (PMID 34307695, 2021). "In prostate cancer, the substrate specificity of KDM1A changes from H3K4me1/2 to H3K9me1/2 through its interactions with ARs." (PMID 29921310, 2018). "Prostate cancer is one of the most common cancers in males, and the overexpression of KDM1A plays an important role in prostate cancer initiation and progression." (PMID 29921310, 2018). "The increased expression of KDM1A, accompanied by a reduction in E-cadherin expression, can be used as a predictive marker for prostate cancer progression and metastasis." (PMID 29921310, 2018). "The inhibition of KDM1A leads to the suppression of gene transcription facilitated by ARs and the inhibition of prostate cancer progression." (PMID 29921310, 2018). "Oncogenic properties of KDM1A have been described in numerous cancers, including prostate cancer, lung cancer, to neuroblastoma." (PMID 27449289, 2016). "In addition, we explored therapeutic targets by investigating FOXA1 interacting protein within proteins encoded by upregulated genes in FOXA1 mutant prostate cancer, and identified six genes—HSP90AB1, KDM1A, FKBP4, H2BC15, WNT7B, and GRB7." (PMID 37958805, 2023). "Similarly, for prostate cancer, KDM1A, BRD4, and PRMT1 were depleted in LNCaP cells as well as AR, FOXA1 and NCOA1, thus serving as positive controls." (PMID 35973998, 2022). "Lysine-specific demethylase 1 (LSD1/KDM1A) is a histone demethylase that removes mono- and dimethyl-lysine 4 of histone H3 (H3K4me1/2) and is overexpressed in various cancer types including breast, lung, and prostate cancer." (PMID 31108893, 2019).
prostate carcinoma (continued). "In prostate cancer, mutations of KMT2 genes (also known as mixed lineage leukemia family methylates) and dysregulation of EZH2 (enhancer of zeste 2 polycomb repressive complex 2 subunit) and LSD1 (lysine-specific demethylase 1, also known as KDM1A) are commonly observed and further enriched in CRPC." (PMID 37663929, 2023). "Furthermore, it has been reported that KDM1A (LSD1) was a target of miRNA-155 in prostate cancer." (PMID 32908449, 2020). "Lysine-specific demethylase 1 (KDM1A/LSD1) removes the mono- and di-methylation from H3K4 and H3K9, and plays an important role in regulating AR-dependent gene expression in prostate cancer." (PMID 36776288, 2023). "Among the epigenetic regulators of AR, lysine-specific histone demethylase 1 (LSD1, also known as KDM1A) was discovered first, and its mechanism has been well studied in prostate cancer." (PMID 32847068, 2020). "KDM1A regulates the expression of vascular endothelial growth factor A (VEGF-A), which is important in prostate cancer progression." (PMID 29921310, 2018). "A relevant example of this modulatory function is the Lysine Specific Demethylase 1A (KDM1A/LSD1) that was recently described as corepressor and coactivator for the androgen receptor (AR) in prostate cancer." (PMID 26117541, 2015). "KDM1A inhibition by HCI-2509 downregulates MYC expression in prostate cancer cells, suggesting that it may act as a promising therapeutic in castration- and docetaxel-resistant prostate cancer." (PMID 33801599, 2021). "Notably, as most of the approved drugs targeting MAOA and KDM1A were monoamine inhibitors used for mental illness or diabetes, we suggest they have a potential to cure FOXA1 mutant primary prostate cancer without lethal side effects." (PMID 37958805, 2023).
acute myeloid leukemia (115 papers, 2012 to 2026). Acute myeloid leukemia (AML) is a group of neoplasms arising from precursor cells committed to the myeloid cell-line differentiation. "In addition, a study indicated that inhibition of KDM1A caused a global elevation of chromatin accessibility in acute myeloid leukemia cells." (PMID 38295985, 2024). "Lysine specific demethylase 1 (LSD1 or KDM1A) is a FAD-dependent histone demethylase which is overexpressed in acute myeloid leukemias (AMLs)." (PMID 42129910, 2026). "Lysine-specific demethylase 1 (LSD1 or KDM1A) has emerged as a promising therapeutic target in acute myeloid leukemia." (PMID 38725484, 2024). "Inhibiting KDM1A in acute myeloid leukemia cells also induces differentiation and reduces the accumulation of blast cells in vivo." (PMID 39458030, 2024). "Drugs targeting KDM1A have entered clinical studies in small cell lung cancer and acute myelocytic leukemia." (PMID 36742386, 2023). "An earlier study has shown that the pharmacological inhibition of KDM1A reduces tumor growth and reactivates the all-trans-retinoic acid differentiation pathway in acute myeloid leukemia (AML)." (PMID 27058897, 2016). "High-level KDM1A expression has also been reported in prostate, bladder, breast, colorectal, gastric and lung cancers as well as sarcomas and acute myeloid leukemia." (PMID 39458030, 2024). "Moreover, KDM1A is also capable of sustaining oncogenic gene expression and impairing differentiation in a number of acute myeloid leukemia subtypes, underscoring its potential therapeutic implications in leukemia." (PMID 35504875, 2022). "Promisingly, three drugs targeting H3K4 demethylases have reached clinical trials: KDM1A inhibitor ORY-1001 for acute myeloid leukemia and small cell lung cancer, KDM1A inhibitor GSK2879552 for myelodysplastic syndromes, and KDM5 inhibitor GS-5801 for chronic hepatitis B infection." (PMID 30616667, 2019). "Given that the demethylase activity of KDM1A is vital for its participating in various diseases such as lung adenocarcinoma and acute myeloid leukemia, we sought to investigate whether the enzymatic activity of KDM1A is indispensable for its pivotal role in the development of NAFLD." (PMID 38295985, 2024). "Currently, numerous natural and synthetic KDM1A inhibitors have been identified in the last decades, and some of which are currently undergoing clinical assessment for the treatment of acute myeloid leukemia (AML), small cell lung cancer (SCLC) as well as some other solid tumors." (PMID 33935733, 2021). "In contrast, nuclear GSK-3β is not only responsible for cancer stem cell self-renewal and glioblastoma tumorigenesis by stabilizing histone demethylase KDM1A but also crucial for acute myeloid leukemia (AML) initiation and aggressiveness in AML via β-catenin independent mechanisms." (PMID 35646902, 2022). "For example, disruption of the KDM1A-GFI interaction, which regulates gene expression, resulted in the promotion of blast cell differentiation in acute myeloid leukemia (AML) with malignant lymphoma with leukemia (MLL) translocations." (PMID 34307695, 2021). "It was shown that the KDM1A gene was highly expressed in tumor samples of lymphoid neoplasm diffuse large B-cell lymphoma (DLBC) and thymoma (THYM) and was lower in acute myeloid leukemia (LAML) compared with normal tissues (p < 0.05)." (PMID 34925656, 2021). "In acute myeloid leukemia (AML), KDM1A overexpression blocks differentiation and results in a poor prognosis." (PMID 30568590, 2018). "GSK-2879552 is a lysine-specific histone demethylase-1A (LSD1 or lysine demethylase 1A, KDM1A) inhibitor and was investigated for its activity against small cell lung cancer (SCLC), acute myeloid leukemia (AML), and myelodysplastic syndrome (MDS), however clinical trials were terminated." (PMID 35625702, 2022).
acute myeloid leukemia (continued). "At present, there are many LSD1/KDM1A inhibitors under clinical trial as a promising future cancer therapy with the majority of these being targeted against small-cell lung cancer (SCLC) and acute myeloid leukemia (AML)." (PMID 36826125, 2023).
leukemia (93 papers, 2012 to 2026). A malignant (clonal) hematologic disorder, involving hematopoietic stem cells and characterized by the presence of primitive or atypical myeloid or lymphoid cells in the bone marrow and the blood. "The expression of KDM1A was shown to be associated with the activation of oncogenes specific for leukemia stem cells." (PMID 29921310, 2018). "KDM1A has been also reported as an essential regulator of leukemia stem cell potential in a murine model of human MLL-AF9 leukemia, with persistence of expression in associated oncogenic signaling, thereby preventing differentiation and apoptosis of leukemic cells." (PMID 28452984, 2017). "SNAI1 is a key modulator of epithelial-to-mesenchymal transition (EMT) and has been linked to leukemia pathophysiology by impairing differentiation and enhancing self-renewal and proliferation of blast cells through its interaction with the histone demethylase KDM1A/LSD1." (PMID 41596324, 2026). "LSD1 (KDM1A) has been found to be overexpressed in several hematological and solid tumors and shown to be required for maintenance of leukemia (e.g. AML)." (PMID 36229595, 2022). "Treatment of leukemia cell lines with KDM1A inhibitors promoted monocytic differentiation (exemplified by CD86 expression) and subsequent cell death at the nanomolar range." (PMID 31649884, 2019). "In vivo KO of KDM1A in murine leukemia cells resulted in prolonged survival, while expression of catalytic inactive KDM1A did not prolong survival." (PMID 31649884, 2019). "Based on these findings it was concluded that both the scaffold function and the catalytic activity of KDM1A need to be inhibited for effective leukemia treatment." (PMID 31649884, 2019). "Using a retroviral transduction assay, an analysis of multiple MLL-FP leukemias revealed overexpression of the H3K4/K9 eraser KDM1A (lysine (K)-specific demethylase 1A)." (PMID 24213472, 2012). "In the primary AML cells, the KDM1A inhibitors inhibit PI3K pathway and activate the MEK pathway, further inhibition of KDM1A sequential the MEK inhibitor significantly promotes leukemia cell apoptosis especially in M5 leukemia, which was associated with protein phosphorylation and RAS mutation." (PMID 35865470, 2022). "One preclinical study demonstrated that LSD1/KDM1A inhibition with a small molecule (ORY-1001) induced H3K4me2 accumulation on KDM1A target genes, resulting in blast differentiation and reduced leukemia burden in cell line and animal models of MLL-rearranged T-acute lymphoblastic leukemia." (PMID 34864823, 2021). "KDM1A is typically reported for its overexpression in various kinds of solid tumors and leukemia." (PMID 34350095, 2021). "Certain types of leukemia and solid cancer types like small cell lung cancer are highly sensitive to both KDM1A knock-down and inhibition, and several selective KDM1A inhibitors are in Phase I and II clinical trials for the treatment of hematological or solid tumor indications." (PMID 32469975, 2020). "Expression of KDM1A is increased in many solid tumors and leukemias [14 and references therein]." (PMID 26461474, 2015). "Interestingly, KDM1A expression is required for the maintenance of MLL-FP leukemias and treatment of MLL-FPs with KDM1A inhibitors had a profound effect on leukemic growth in vitro as well as in vivo." (PMID 24213472, 2012). "The combination of KDM1A inhibitor and ATRA can promote the induction and differentiation of leukemia cells by ATRA." (PMID 38322990, 2024). "Recent studies show that the small molecules that target KDM1A disrupt the GFI1/1B–CoREST interaction and that this is key to inducing terminal differentiation of leukemia cells." (PMID 31649884, 2019). "Recent studies have suggested combinatorial therapies, i.e., approaches involving the inhibition of DOT1L (an H3K79 methyltransferase) and the bromo-domain protein BRD4, together with the inhibition of KDM1A, to treat MLL-rearranged leukemia." (PMID 29921310, 2018).